CXCL12 (C-X-C motif chemokine ligand 12)
Diseases named in the same sentence as CXCL12 in open-access papers (continued):
Sharing a sentence is not in itself a finding about the gene and the disease.
tumor (continued). "It is thought that CXCR4 and CXCL-12 can be evaluated together in terms of the tumor microenvironment and used in microenvironment modeling in drug studies." (PMID 36551144, 2022). "In pre-clinical models of PDAC, higher expression of CXCL12 secreted by CAFs increased pancreatic cancer cell invasion and promoted tumor growth by preventing circulating-T-lymphocyte (CTL) infiltration." (PMID 36077755, 2022). "It was also reported that elevated expression levels of CXCL12/SDF-1 chemokine and its receptor CXCR4 were associated with increased tumour growth and spread." (PMID 36510219, 2022). "We predict that the emergence of anti-tumor T cell clones promoted by the CXCR4/CXCL12 axis should synergize with current immunotherapies, which remove the brakes of T cells once they recognize the antigen." (PMID 35565443, 2022). "The receptor CXCR4 together with one of its chemokines, CXCL12 (also known as SDF-1), have been shown to play a key role in the tumor-stromal communication affecting cancer growth, angiogenesis and metastasis formation." (PMID 35397601, 2022). "In fact, the expression of key neutrophil-secreted chemokines, including CCL3, CCL4, CCL20, and CXCL12, was increased in the tumor supernatants of mice treated with 7HP349." (PMID 35552271, 2022). "The anti-CXCL12 aptamer can inhibit tumor-supporting pathways and mobilize CLL cells away from their protective microenvironment, thereby inducing apoptosis and chemotherapy sensitization in these leukemic cells." (PMID 35056696, 2022). "In contrast to the dormancy-inducing effect of LIF, CXCL12 and Gas6, the inflammatory cytokine IL-1β promoted tumour proliferation and subsequently triggered overt metastasis of breast tumour cells." (PMID 36307871, 2022). "JG6 is a new marine-derived oligosaccharide that has been demonstrated to reduce angiogenesis and tumor metastasis by inhibiting CXCL12/CXCR4." (PMID 35080679, 2022). "Two independent studies demonstrated that AMD3100 promotes T cell infiltration into the tumor, by releasing them from the CXCL12-rich surrounding stroma." (PMID 33603130, 2022). "Small molecules (chemokines), particularly CXCR4 and its ligand CXCL12, are overexpressed in the tumour microenvironment of most malignant tumours." (PMID 36140541, 2022). "Previous studies have shown that CXCL12 wraps tumor cells through binding to CXCR4 and thereby prevents effector T cells from contacting cancer cells and consequently leads to immune escape/immunosuppression activities." (PMID 35681617, 2022). "ACKR3 has a primary role as mediator of CXCL12 activity and has pleiotropic roles in tumor development." (PMID 36253784, 2022). "Accumulated evidence indicated the critical roles of the CXCL12 − CXCR4 axis in tumor proliferation, progression, vascularization, and migration as well as the formation of an immunosuppressive TME by the exclusion of immunoreactive cells like T-cells." (PMID 35812726, 2022). "CXCR4, a receptor of CXCL12, was also positively correlated with MT1X and is associated with tumor cell angiogenesis and proliferation." (PMID 36149322, 2022). "CXCL12 chemokines have a high expression of the epidermal growth factor and promotes the formation of new vessels in the tumor cells, consequently increasing the chances of metastasis." (PMID 36518665, 2022). "Chemokine ligand 12 (CXCL12), also known as stromal cell-derived factor-1 (SDF-1), is present in liver sinusoidal endothelial cells (LSECs), tumor cells, and hepatic stellate cells." (PMID 35883127, 2022). "Taken together, these data support a model wherein GC tumors secrete chemokine CXCL12 to recruit neutrophils into the tumor environment via the CXCL12‐CXCR4 interaction." (PMID 34957697, 2022). "Several lines of evidence currently oppose the possibility that the observed diverse migratory, invasive, and apoptotic responses of the various tumor cells to a combination of CXCL12 and CXCL11 would be due to the differential use of CXCR3A and CXCR3B." (PMID 36539774, 2022).
tumor (continued). "Macropinocytosis can be induced in macrophages by stimuli other than CSF1, including lipopolysaccharide (LPS), the chemokine CXCL12 and the tumor promoter phorbol 12-myristate 13-acetate (PMA)." (PMID 35107133, 2022). "The suppressive amino acids did not inhibit macropinocytosis in response to lipopolysaccharide, the chemokine CXCL12, or the tumor promoter phorbol myristate acetate." (PMID 35107133, 2022). "It is reported that the expression of CXCR4/CXCL12 is increased due to the hypoxic tumor environment, which is HIF-lα dependent." (PMID 36551144, 2022). "Mast cells, which can be both tumor-suppressing and tumor-promoting, can be recruited by CAFs via CXCL12 in a CXCR4-dependent manner." (PMID 36010899, 2022). "Fibroblast-derived CXCL12 facilitated tumor cell intravasation and limited T cell-mediated tumor control." (PMID 36119108, 2022). "C25 actively secretes FGF7 and CTGF, which promote CAF growth and tumor angiogenesis, and CXCL12, which interacts with CXCR4 to block and deplete the T-cell response." (PMID 35664733, 2022). "Here, CXCL12 reduces their efficiency as APCs and decreases their immune response, facilitating tumor growth." (PMID 35565443, 2022). "The CXCL12/CXCR4 axis represents one of the most intensively studied pathways in the tumor tropism of MSCs." (PMID 36324128, 2022). "At first, when a fibroblast is in the early stages of activation, SLIT2 increases and inhibits the expression of CXCL12, leading to the prevention of tumour growth and metastasis." (PMID 36555218, 2022). "This likely occurs via the lower expression of CXCL12 in the primary tumor and high expression outside the tumor, creating a gradient that precipitates invasion and spread." (PMID 36358665, 2022). "CXCL12 is a chemokine that plays a key role in promoting tumor progression and orchestrating the recruitment of immune and stromal cells within the TME." (PMID 35443745, 2022). "Overall, these data demonstrate that CXCL12 signaling promotes the glucose metabolism through two key pathways that drive tumor progression: glycolysis and the pentose phosphate pathway." (PMID 35681470, 2022). "Insulin-like growth factor 1 (IGF1), VEGF, PDGF, FGF, and CXCL12 can promote tumor angiogenesis, proliferation, migration, and immunosuppression through paracrine production." (PMID 35965504, 2022). "We investigated the activation of the key ERK1/2 tumor progression cascade in response to exogenous CXCL12 in the different BC subtype models." (PMID 36233192, 2022). "CXCL12 is also a chemokine that promotes migration of macrophages across the endothelial barrier into the tumor environment." (PMID 36045408, 2022). "The CXCL12/CXCR4 axis governs TAMs’ migration into hypoxic tumor areas through the endothelial barrier." (PMID 36303138, 2022). "Overall, our comprehensive analysis identified novel PCa TEC targets and highlights CXCR4/CXCL12 interaction as a potential novel target to interfere with tumor angiogenesis in PCa." (PMID 35717322, 2022). "In 2013, Feig and colleagues theorized that fibroblast cells in the tumor microenvironment (TME) produced the C-X-C motif chemokine 12 (CXCL12), the ligand of CXCR4, which antagonizes and blocks the immune response from killing PDAC cells." (PMID 35797269, 2022). "ECs in the tumor microenvironment overexpress CXCR4 in response to hypoxia and the secretion of CXCL12 by tumor cells and cells in the tumor microenvironment, recruits ECs into the tumor." (PMID 35155581, 2022). "Proximity Ligation Assays (PLA) indicate that CXCR4 and CD47 physically interact on the surface of tumor cells; the binding of CXCL12 to CXCR4 leads to the co-internalization of the CXCR4-CD47 complexes, and therefore to the decrease of surface CD47." (PMID 35565443, 2022). "g, CCL1, CCL5, CCL7, CXCL8, and CXCL12) drive the recruitment of MDSCs to OC tumor sites via the CCR2, CXCR4, and CCR5 axes." (PMID 36532066, 2022).
tumor (continued). "Targeting the CXCL12/CXCR4 axis in multiple cancer models, including prostate and breast cancer, reduces tumor burden and metastatic susceptibility by preventing TAM infiltration." (PMID 36303138, 2022). "Otherwise the immunosuppressive cells suppress the function of CD8+ T cells and NK cells by secreting cytokines such as EGF, TNF-α, CXCL12, IL-10 and IL-6, thereby ensuring the survival of tumor cells." (PMID 35454769, 2022). "Given the established role of the HIF-1/CXCL12/CXCR4 pathway in tumor vasculogenesis, antagonists to this pathway are predicted to display clinical potency as anti-vasculogenic agents." (PMID 36568151, 2022). "The disease recurrence rates in the subgroup of 29 adenocarcinoma patients tended to correlate with high CXCL12 expression in the tumor." (PMID 35740564, 2022). "They attract tumor cells to the bone tissue by secreting CXCL12, an already mentioned chemotactic and adhesion molecule." (PMID 34212564, 2021). "We found that the expression of CXCL1/3/5/6/8/9/10/11/13/16/17 was up-regulated in tumor tissues, while the expression of CXCL12/14 was down-regulated." (PMID 34321012, 2021). "Perivascular CAF-derived CXCL12 is also implicated in attracting CXCR4+ macrophages toward blood vessels, which in turn leads to tumor cell intravasation in murine models." (PMID 34203869, 2021). "HBMECs promoted tumor cell migration and adhesion under hypoxic condition through producing increased CXCL12 expression." (PMID 34093792, 2021). "The CXCL12/CXCR4 axis greatly contributes to certain tumor-mediated metastases and is thought to be a potential target of CXCR4 antagonists." (PMID 34722241, 2021). "This inhibition was associated with a significant suppression of the tumor CXCR4/CXCR7 and the stimulation of human CXCL12 expression." (PMID 34834449, 2021). "Highly expressed CXCL12 has been found in the most common sites of tumor metastasis, including lymph nodes, lung, liver, and bone marrow." (PMID 33710803, 2021). "Significantly lower expression of CXCL12 was reported in tumor tissues among various tumor types, including BLCA (p < 0.001)." (PMID 34801033, 2021). "CXCL12 is a key factor that can recruit immunosuppressive bone marrow-derived cells and thus contribute to the immunosuppressive tumor microenvironment (TME)." (PMID 33753481, 2021). "In cancer, CXCL12 regulates homing via the establishment of a hypoxia-dependent gradient that drives BMDCs to the CSC niche in the primary tumor or by building up the metastatic niche where needed, to ensure CSC growth and the generation of new vasculature." (PMID 33530455, 2021). "Silencing of CXCL12 by transforming growth factor-β in mesenchymal stromal cells of the primary tumor site promoted the tumor metastasis by increasing the expression of CXCR7, a CXCL12 receptor." (PMID 33833937, 2021). "Tumor-secreted GM-CSF, CXCL12, and CCL2 attract monocytes to the TME and drive their differentiation into M2 TAMs, which then promote angiogenesis through secretion of Matrix Metalloproteinase 9 (MMP9) and Vascular Endothelial Growth Factor A (VEGF-A)." (PMID 34830776, 2021). "The CXCR4/MIF and CXCR4/CXCL12 axis had been reported as the key elements of MSC migration toward tumor cells." (PMID 33933086, 2021). "The authors validated their findings in patient samples and reported the upregulation of PDGFRα, PDGFRβ, and CXCL12 in tumor cells." (PMID 33530455, 2021). "CXCL12 binds to metastasis-related proteins in GC cells 24, and is therefore a biomarker of tumor prognosis, metastasis, and chemo-resistance." (PMID 33854601, 2021). "In leukemic conditions, such as T-cell acute lymphoblastic leukemia, CXCL12 knockout in ECs suppressed tumor development, indicating a dependency of the tumor on the vascular environment." (PMID 35118078, 2021).
tumor (continued). "BCAF secretes a variety of growth factors and cytokines, such as the transforming growth factor β (TGF-β), VEGF, and the C-X-C motif chemokine ligand 12 (CXCL12) that promotes tumor growth, metastasis, and invasion." (PMID 34944738, 2021). "These TAMs are recruited to the tumor site by stromal cell derived factor 1 (CXCL12), a chemokine produced within the TME." (PMID 34988021, 2021). "We concluded that under hypoxia, HBMEC expressed more CXCL12 that promoted DLBCL tumor cells to migrate and adhere to vessels." (PMID 34093792, 2021). "Mediating its effects by binding to its major corresponding receptor, CXCR4, CXCL12 is implicated in inflammatory responses, autoimmune diseases, T cell homing, angiogenesis, CAFs activation, EMT, tumor progression, metastasis, and therapy resistance." (PMID 34064859, 2021). "Further studies revealed that targeting CAFs leads to decreased CXCL12 release and decreased extracellular matrix deposition, which reduces the barrier to T-cell infiltration and facilitates greater tumor inhibition." (PMID 34490078, 2021). "Among these factors regulating the trafficking of tumor cells, CXCL12 seems to be especially relevant, as metastatic cells express its major receptor, CXCR4." (PMID 34112253, 2021). "One possible interpretation is that cervical expression of CXCL12 is heterogeneous, tending to be inhibited as the tumor grows." (PMID 34321012, 2021). "One of the key mechanisms by which they achieve this is via secretion of the CXCL12 chemokine, which facilitates immune evasion by blocking T cell trafficking to the vicinity of tumour cells." (PMID 34944794, 2021). "The CXCR4/CXCL12 pathway is responsible for tumor metastasis, progression, induction of angiogenesis, and resistance to apoptosis." (PMID 34203877, 2021). "CXCL12 secreted by PDAC lesions attracts Schwann cells (SCs) of nearby nerves to migrate into tumor deposits." (PMID 35008248, 2021). "The pro-tumor environment established by TAMs has also been described in other tumor types such as astrocytoma, in which CXCL12 is depicted as a critical mediator of tumor progression and TAM infiltration." (PMID 33530455, 2021). "Soluble CXCR4 expressed by GMOVs binds to CXCL12 secreted by tumor cells as a decoy receptor and inhibits the effects of CXCL12 on angiogenesis, metastasis, and recruitment of MDSCs." (PMID 33546172, 2021). "We noticed higher CXCL12 expression in the tumor nests than in the stroma as also documented in human tumors." (PMID 33988305, 2021). "CXCR4 expression is elevated in tumor cells, and high levels of CXCL12 are expressed in tumor metastases target tissues such as lung, liver, brain, and bone." (PMID 33390169, 2021). "It is constitutively expressed by MSCs, where it is responsible for the retention of hematopoietic progenitor and stem cells and CXCL12 was largely expressed in senescent tumor cells, where it was related to cancer cell migration and metastasis." (PMID 33491125, 2021). "In transcellular intravasation CAFs exert an active role, producing CXCL12 and TGFb that induce the proliferation of tumor cells and protect them in the tumor embolus, a nest of tumor cells embedded in endothelium." (PMID 34885027, 2021). "When the Ly1 tumor cells were co-cultured with HBMECs under hypoxic condition, chemokine CXCL12 significantly promoted tumor cell migration." (PMID 34093792, 2021). "These factors favor the selection of tumor cell clones which are primed to metastasize to and adhere to bone, a microenvironment being itself rich in CXCL12." (PMID 34064859, 2021). "In brief, CXCL12 secreted in the TME recruits CD4+CD25+ Treg cells to the tumor sites to contribute to the growth and prosperity of HCC." (PMID 34386499, 2021). "CXCL9 (p = 0.027), CXCL10 (p < 0.001), CXCL11 (p = 0.002) and CXCL13 (p < 0.001) were significantly up-regulated in tumor tissues compared with tumor-adjacent tissues, while the expression of CXCL12 (p = 0.149) was down-regulated." (PMID 34321012, 2021).
tumor (continued). "One of them, CXCL12/SDF-1, shows strong expression in IL-7-producing fibroblasts, with the CXCL12/CXCR4 axis impacting tumor cell stemness promoting BC growth." (PMID 34337083, 2021). "In SS patients, the impaired expression of CD26 on tumor cells was responsible for uncontrolled accumulation of CXCR4+ T cells in the skin where CXCL12 is abundantly expressed." (PMID 34503058, 2021). "We found that CXCL12 was upregulated in p16INK4A positive senescent tumor cells in three out of five patients." (PMID 33643790, 2021). "CXCL12 regulates adhesion of tumor cells with laminin, fibrinogen, stromal cells and endothelial cells (ECs) by activating cell surface adhesion molecules." (PMID 33937018, 2021). "In this study, it appears that p50 NF-κB activity in PSCs promoted tumor growth by increasing expression of CXCL12 and preventing cytotoxic CD8+ T cells from infiltrating the tumor and killing PDAC cells." (PMID 34572737, 2021). "It is well documented that the binding of CXCL12 (also known as SDF-1) to its receptor like CXCR4 or CXCR7 remarkably promotes tumor progression including OS." (PMID 34956899, 2021). "CXCL12 has been shown to be a stimulatory chemokine related to tumour neovascularization and to be involved in promoting the migration and invasion of cancer cells." (PMID 34358255, 2021). "In this review, we focus on the contribution of the CXCL12/CXCR4/CXCR7 axis in signaling in tumor/TME cells and we evaluate the possible combined targeting of CXCR4 and CXCR7." (PMID 33937018, 2021). "The chemokine stroma-derived factor SDF-1 (also called CXCL12) plays multiple roles in tumor pathogenesis." (PMID 34579743, 2021). "The CXCL12/CXCR4 axis constitutes one of the most important signaling pathways that regulates tumor growth, angiogenesis, and metastasis, and it is a predictive factor for survival in patients." (PMID 33530455, 2021). "CXCL12, stained in cytoplasm, was mainly expressed in nerve cells and occasionally detected in tumour cells of 51.9% (82/158) SACC specimens, and 10% (2/20) in normal salivary gland was weak expression." (PMID 34170080, 2021). "The strong negative correlation found between tumor growth and CXCL12 expression in cancer cells suggests a major role of CXCL12 in controlling tumor progression." (PMID 34834449, 2021). "CXCL12 stimulates survival and growth of neoplastic cells, promotes tumor angiogenesis by stimulating VEGF and recruiting endothelial progenitor cells to the TME, and attracts Tregs, MDSCs, and peripheral DCs into the TME." (PMID 33407605, 2021). "The differential quantitative expression of the CXCR4/CXCR7 receptors and their ligand CXCL12 was evident between the tumor samples from a pilot cohort of n = 22 ACC patients and n = 26 normal adrenals." (PMID 34834449, 2021). "The interactions facilitated by CXCL12/CXCR4/CXCR7 axes seem to be strongly linked to CSC “stem”-like features, tumor progression, and metastasis promotion." (PMID 33530455, 2021). "In this context, it has been shown that cancer-associated fibroblasts (CAFs) in the tumor stroma can prime tumor cells for dissemination to the bone via secretion of C-X-C motif chemokine ligand 12 (CXCL12, also known as SDF-1)." (PMID 34831167, 2021). "The nanoparticles can specifically down-regulate the expression of CXCL12 in CAFs, significantly inhibiting tumor cell invasion and migration, and tumor angiogenesis." (PMID 34490078, 2021). "The CXC chemokine receptor type 4 (CXCR4) receptor and its ligand, CXCL12, are overexpressed in various cancers and mediate tumor progression and hypoxia-mediated resistance to cancer therapy." (PMID 33753481, 2021).